CRP (C-reactive protein)
Diseases named in the same sentence as CRP in open-access papers (continued):
Sharing a sentence is not in itself a finding about the gene and the disease.
cholestasis (34 papers, 2009 to 2026). Impairment of the bile flow caused by obstruction within the liver, or outside the liver in the bile duct system. "In contrast, the parameters reflecting inflammatory (CRP), hemodynamic (serum urea and creatinine), and coagulation (thrombocyte count) status showed an association with fewer cholestasis-related parameters, and these associations were more likely to be spurious." (PMID 39202194, 2024). "In basic laboratory tests, the total bilirubin level was 8.82 mg/dL, showing signs of cholestasis, elevated C-reactive protein (CRP) at 68 mg/dL, and a decreased hemoglobin level at 8.1 g/dL." (PMID 39997389, 2025). "Cholestasis parameters, such as alkaline phosphatase (AP), gamma glutamyl transferase (GGT), bilirubin as well as the C-reactive protein (CRP) were elevated at baseline representing cholestasis and cholangitis." (PMID 39500762, 2025). "Lost to follow-up for nine years, he presented with acute lithiasis cholangitis characterized by fever, conjunctival jaundice, leukocytosis, CRP elevation, and biochemical signs of cholestasis." (PMID 38669806, 2024). "The SLC10A1 mRNA expression showed a 44-fold variation (coefficient of variation: 66%) and was significantly affected by age, inflammation (i.e., C-reactive protein [CRP] levels), cholestasis, smoking, and alcohol consumption." (PMID 35806468, 2022). "The third transplantation plus splenectomy led to a persistent normalization of liver function and cholestasis, but VREfm was still detected in the abdomen, with ongoing elevated CRP levels." (PMID 34578366, 2021). "Furthermore, in group comparisons expression of NFIA but not of the other NFI genes was lower with alcohol use, elevated levels of CRP (inflammation), cholestasis and the use of CYP inducers." (PMID 41106572, 2025). "In agreement with previous data which we had described for the hepatic uptake transporters SLC22A1/OCT1 and SLCO1B1/OATP1B1 cholestasis, alcohol consumption, and inflammation determined by C-reactive protein altered SLC10A1/NTCP expression whereas age and gender are of minor importance." (PMID 35806468, 2022). "Following detailed examination, our patient did not have any other disease associated with cholestasis, and her symptoms gradually improved as CRP decreased." (PMID 34059097, 2021). "Laboratory analyses revealed normal hemoglobin and platelets, leukocytosis with a high lymphocytes and monocytes count, an increased level of C-Reactive Protein (CRP), transaminases, lactate dehydrogenase (LDH) and total/direct bilirubin with cholestasis." (PMID 40611140, 2025). "Laboratory tests revealed signs of inflammation, including hyperleukocytosis (13,000/mm3) and elevated C-reactive protein (CRP) at 90 mg/L, as well as cholestasis characterized by markedly elevated alkaline phosphatase (350 U/L) and gamma-glutamyl transferase (220 U/L)." (PMID 40585681, 2025). "Laboratory tests for infection, including blood counts, C‐reactive protein (CRP), renal function, and cholestasis markers, are not always altered and are, therefore, nonspecific." (PMID 41425521, 2025). "Similarly, augmented proportions of TP+ cells, CD3+P+ cells and CD4+P+ cells were found in patients elected for OC, which preoperatively, had higher preoperative levels of CRP, AP, B, AST and ALT, suggesting that preoperative inflammation and cholestasis affected the perforin-related events." (PMID 19436761, 2009).
microcytic anemia (34 papers, 2013 to 2025). Anemia in which the red blood cell volume is decreased. "Blood tests found microcytic anemia (Hemoglobin (Hb): 9 g/dL, mean corpuscular volume of 80 fl) with both iron and vitamin B12 deficiency (ferritin: 12 μg/L, B12 93 pmol/L (138–652 pmol/L)) and elevated levels of acute phase reactants (i.e., C-reactive protein (CRP): 45 mg/L)." (PMID 34359324, 2021). "Laboratory findings included a normal white blood cell count, mild microcytic anemia, elevated C-reactive protein (CRP) at 8.3 mg/dL (normal: 0.0–0.8 mg/dL), and elevated fecal calprotectin at > 1250 μg/g (normal ≤ 49 μg/g)." (PMID 40756461, 2025). "Her initial tests showed an elevated C-reactive protein (CRP) as well as microcytic anemia based on the patient's low mean corpuscular volume (MCV) and hemoglobin." (PMID 39624544, 2024). "Laboratory investigations were normal except for the presence of microcytic anemia and a mild increase in C-reactive protein (CRP)." (PMID 34082764, 2021). "Laboratory studies revealed neutrophilia, microcytic anemia, and elevation of both erythrocyte sedimentation rate and C-reactive protein rate." (PMID 24839565, 2014). "Preliminary complete blood counts identified a microcytic anemia in 57% (four of seven) of the patients, elevated levels of CRP in 43% (three of seven) and increased erythrocyte sedimentation rate in 28.5% (two of seven)." (PMID 25434739, 2014). "Hypochromic microcytic anemia (Hb 86g/L) and elevated ESR (59 mm/h) and CRP (148.9 mg/L) were noted in laboratory testing." (PMID 34745107, 2021). "Laboratory investigations showed microcytic anemia in 2 cases (III.3, III28), and inflammatory markers were elevated including erythrocyte sedimentation rate (100 mm/h) and C-reactive protein (70 mg/dL) in one case (III.28)." (PMID 34657628, 2021). "One relative (ID 24) had a TSAT/hepcidin ratio below the reference range (TSAT/hepcidin 0.8%/nM), but this is not consistent with an IRIDA phenotype due to the absence of microcytic anemia, a TSAT > 15%, and the presence of inflammation (CRP 45 mg/L)." (PMID 35893046, 2022).
brucellosis (33 papers, 2012 to 2026). Brucellosis is a bacterial infection that spreads from animals to people via unpasteurized dairy products or by exposure to contaminated animal products or infected animals. "The data from this study strongly support the conclusion that CRP levels are valuable diagnostic indicators for early brucellosis screening." (PMID 38088960, 2023). "Patients with complicated brucellosis tend to have higher CRP levels than those with uncomplicated brucellosis, and elevated CRP levels are significantly associated with brucellosis complications." (PMID 38088960, 2023). "Elderly men brucellosis patients with arthralgia, wrist joint pain and elevated CRP were at high risk of positive RF." (PMID 34543280, 2021). "We analyzed risk factors associated with chronic brucellosis (duration ≥ 4.4 months) in 200 patients, including sex, age, infection site, imaging findings, culture results, surgical intervention, length of hospital stay, and CRP ≥ 1.21 mg/L." (PMID 41208962, 2025). "Likewise, elevated CRP was positively associated with positive RF among brucellosis patients in this study." (PMID 34543280, 2021). "Same to Akya A reported serum CRP can be used as valuable markers in the preliminary diagnosis of brucellosis." (PMID 40557315, 2025). "Hemoglobin and platelet values were significantly lower in brucellosis cases compared to the control group (p<0.001), and C-reactive protein and ferritin were significantly higher (p<0.001)." (PMID 39841697, 2025). "The knee joint is the most commonly affected site, and CRP is a valuable biomarker for differentiating brucellosis cases." (PMID 40557315, 2025). "The levels of ESR and CRP were higher in patients with complicated brucellosis compared to those with uncomplicated brucellosis (P < 0.001)." (PMID 38374211, 2024). "Vitamin D levels declined (46.4%) and CRP levels rose (from 7.5 mg to less than 1 mg) throughout the acute and chronic stages of brucellosis." (PMID 37640734, 2023). "A complete blood count, C-reactive protein (CRP), blood culture, serologic test for typhoid fever, and brucellosis were done, as well as MRI in order to investigate a potential cerebral abscess, which showed a right sub-acute temporoparietal infarction." (PMID 37427240, 2023). "A retrospective evaluation and review of the clinical manifestations and complications in 1,028 cases of brucellosis showed that the most common laboratory finding was a high C-reactive protein level." (PMID 38088960, 2023). "The CRP assay is a valuable index for diagnosing and monitoring the treatment of patients with brucellosis." (PMID 38088960, 2023). "Serum levels of trace elements, vitamin D, CRP, and biochemical parameters were measured in rats involved in brucellosis." (PMID 37640734, 2023). "Our study also assessed the correlation of Brucella antibody titers with the clinical picture of brucellosis including the most common symptom of arthralgia, as well as fever, leukocytosis, and elevated inflammatory markers, CRP and ESR." (PMID 33531081, 2021). "Elevated CRP levels were detected in 49% (121/248) of all the cases that had brucellosis, 59% (54/92) of the cases that had liver involvement, and 43% (67/156) of the control group." (PMID 33178515, 2020). "Laboratory research is typically unhelpful in the differential diagnosis of pediatric brucellosis because CRP, leukocyte count, and ESR are normal or slightly raised in most cases." (PMID 33178515, 2020). "In our study, the highest levels of prolidase, ESR, and CRP were seen in the patients with acute brucellosis." (PMID 31651117, 2019). "In this study, we investigated the relationship between the immune reaction and several clinical indicators (WBC, ALT, AST, PLT, ESR, and CRP) in patients with brucellosis." (PMID 31686983, 2019). "A positive correlation was detected between inflammatory markers, ESRs, CRP levels, and cytokine levels in patients with brucellosis." (PMID 31686983, 2019).
brucellosis (continued). "It is reported in various studies that CRP especially is a useful marker of the activity of brucellosis and in monitoring the efficiency of the given treatment." (PMID 26557287, 2012). "Similarly, C-reactive protein (CRP) levels were significantly higher in the rickettsiosis group, with a mean of 6.49 ± 7.68 mg/dL, compared with 1.74 ± 2.12 mg/dL in the brucellosis group (p < 0.001)." (PMID 40094918, 2025). "In contrast, brucellosis typically follows a subacute course, explaining the lower CRP levels seen." (PMID 40094918, 2025). "In this study, increased erythrocyte sedimentation rate, elevated proportions of monocytes/macrophages, elevated levels of CRP, decreased hemoglobin, and reduced platelet counts were all relatively common laboratory manifestations observed in patients with brucellosis." (PMID 40400681, 2025). "Several studies have investigated the role of ESR and CRP levels in the diagnosis of brucellosis." (PMID 40400681, 2025). "This suggests that CRP and SAA2 may hold diagnostic value in monitoring the progression of Brucellosis to chronic infection." (PMID 39872944, 2024). "Serum CRP level was evaluated before and after brucellosis treatment." (PMID 37640734, 2023). "Furthermore, CRP levels and D-dimer assays can be helpful indicators for diagnosing and monitoring human brucellosis." (PMID 38088960, 2023). "In addition, CRP was detected in 49% of all patients suffering with brucellosis and in 59% of the cases that had liver involvement, and was this statistically significant in patients with hepatic involvement." (PMID 33178515, 2020). "In patients with acute brucellosis, CRP and ESR levels were significantly increased." (PMID 32660627, 2020). "Indirect inflammatory markers such as NLR, PLR, MPV, red distribution width, and CRP levels may be helpful for follow-up of brucellosis." (PMID 33027411, 2020). "Different elevated levels of ESR and CRP are predictable during any infections, like brucellosis." (PMID 23930340, 2013). "Laboratory evaluation revealed that serum ferritin, procalcitonin (PCT), C-reactive protein (CRP), and creatinine (Cr) levels were markedly higher in the scrub typhus group compared with the brucellosis group." (PMID 41824464, 2026). "When the data from all patients was considered, the mean values of leukocyte, ESR, CRP, AST, and ALT, which were higher before treatment, decreased after brucellosis treatment." (PMID 41305421, 2025). "Among patients with brucellosis, the most significant changes after brucellosis infection were increased erythrocyte sedimentation rate (ESR) and increased C-reactive protein (CRP) levels, with 169 cases (29.09%) and 134 cases (23.06%), respectively." (PMID 40400681, 2025). "The cut-off values of CRP and ESR for diagnosing brucellosis complications were > 5.4 mg/L (sensitivity 73.4% and specificity 51.9%) and > 25 mm/h (sensitivity 47.9% and specificity 71.1%)." (PMID 40400681, 2025). "This study identified CRP and ESR as indicators of focal involvement in brucellosis, with a cutoff value of 5.4 mg/L for CRP and 25 mm/h for ESR." (PMID 38374211, 2024). "C-reactive protein (CRP) was positively correlated with the erythrocyte sedimentation rate (ESR) (R = 0.409, P = 0.001) in patients with brucellosis." (PMID 34592958, 2021). "The detection of the correlation between blood culture positivity and elevated liver enzymes, CRP and ESR levels, and low hemoglobin and platelet levels were considered to be consistent with the fact that brucellosis is a pathogen that involved the RES." (PMID 33178515, 2020). "In some studies, 38% to 87% of patients with brucellosis had elevated ESR, and 34% to 81% of them had positive values of CRP." (PMID 23930340, 2013). "It is known that CRP and ESR, recognized as traditional inflammation markers, increase in brucellosis cases and decrease to normal levels after treatment." (PMID 26557287, 2012).
brucellosis (continued). "Regarding inflammatory serum markers, patients who presented with BEO had C-reactive protein (CRP) levels (mg/dL) of 11 vs. 1.8 for the non-EO brucellosis patients." (PMID 41209731, 2025). "The findings demonstrated that while these proteins were elevated during the acute phase of Brucellosis, CRP, FGB, LYZ, and AAT did not return to the baseline levels observed in healthy controls in chronic patients." (PMID 39872944, 2024). "Regarding laboratory findings, a significantly lower white blood cell count (P <0.001), C-reactive protein level (P = 0.028) and procalcitonin level (P = 0.002) were observed in patients with brucellosis than in patients without brucellosis." (PMID 36802393, 2023). "Many studies have shown that CRP and PCT are sensitive indicators for the diagnosis of Brucellosis." (PMID 34610810, 2021). "The correlation detected between blood culture positivity and elevated liver enzymes, CRP and ESR levels, low hemoglobin and platelet levels were considered to be consistent with the fact that brucellosis is a pathogen that involves the reticuloendothelial system." (PMID 33178515, 2020). "Increased levels of AST, ALT, GGT, CRP, and ESR may have a complementary role in the differential diagnosis of childhood brucellosis." (PMID 32140324, 2020). "Despite the insufficient levels of specificity and sensitivity, we are of the opinion that high levels of AST, ALT, GGT, CRP, and ESR may have a complementary role in the differential diagnosis of childhood brucellosis." (PMID 32140324, 2020). "As a result, clinicians chiefly rely on other laboratory tests to evaluate patients with brucellosis, such as agglutination test, white blood cell (WBC) counts, platelet (PLT) counts, liver function tests, erythrocyte sedimentation rate (ESR), and C-reactive protein (CRP)." (PMID 34335092, 2021). "Receiver operating curves were plotted to compare predictive values of CRP (area under curve (AUC): 0.635, p= 0.001), ESR(AUC:0.701, p<0.001), AST(AUC: 0.595, p=0.015), ALT(AUC:0.604, p=0.007), and GGT(AUC:0.593, p=0.016) in 332 patients with suspected brucellosis." (PMID 32140324, 2020). "Therefore, increased CRP and ESR have been reported to be involved in active disease and are often considered as useful criteria for the diagnosis and follow-up on the effectiveness of treatment in brucellosis." (PMID 31651117, 2019). "Considering the prerequisites for knee arthroplasty, preoperative inflammatory markers such as CRP and ESR were presumably negative, indicating no overt active infection, which complicated preoperative exclusion of brucellosis." (PMID 41517743, 2026). "In summary, CRP and ESR are important markers to diagnose brucellosis; however, their sensitivity and specificity are not sufficiently large, which requires other laboratory diagnostic indicators and diagnostic methods to compensate for their shortcomings in diagnosing brucellosis." (PMID 40400681, 2025). "Notably, P02741 (CRP) and P0DJI9 (SAA2) showed differential expression across all three groups, while P0DJI98 (SAA1) did not exhibit differential expression between the chronic Brucellosis group and the healthy controls." (PMID 39872944, 2024).